IFNAR1 (interferon alpha and beta receptor subunit 1)
Diseases named in the same sentence as IFNAR1 in open-access papers (continued):
Sharing a sentence is not in itself a finding about the gene and the disease.
ZIKV infection (continued). "First, ZIKV infection of astrocytes breaks down the blood-brain barrier of Ifnar1−/− mice, leading to a large influx of CD8+ T cells that promotes paralysis." (PMID 37191498, 2023). "Since it has been well proven that murine IFN-I response restrains ZIKV infection, immunocompromised mice or WT mice treated with IFNAR1 antibodies were employed to establish animal models of ZIKV infection." (PMID 35972780, 2022). "In summary, our study showed that intensity of immune responses during ZIKV infections in humans can be regulated by IFNAR1 rs2257167 genotypes." (PMID 34899713, 2021). "Specifically, our results demonstrated that newborns who carried the CG/CC genotypes of SNP rs2257167 (IFNAR1) had a 3.4 higher risk of developing CZS, resulting from ZIKV infection during pregnancy, compared to those with the GG genotype." (PMID 34899713, 2021). "When myelinating cultures from Ifnar1 KO mice, all central nervous system cells were vulnerable to ZIKV infection, especially oligodendrocytes." (PMID 33717035, 2021). "Recently, BALB/c mice treated with an anti-IFNAR1 monoclonal antibody as well as neonate BALB/c mice have also been used to model ZIKV infection in adults as well to study neuropathogenesis, respectively." (PMID 32373111, 2020). "IFNAR1 antibody was delivered to pregnant mice at E5.5 and E6.5, one day before and right after ZIKV infection at early placentation." (PMID 32392268, 2020). "In our ZIKV vertical transmission model, we crossed Ifnar1−/− female mice with WT male mice, and found that 77% of the pregnant mice produced Ifnar1+/− fetuses when examined on E18.5 after ZIKV infection." (PMID 32628667, 2020). "To determine the cross-protective role of CD8 T cells against ZIKV infection, we transferred purified CD8 T cells from JEV-immunized mice to naïve HHD Ifnar1–/– mice prior to ZIKV infection." (PMID 33101303, 2020). "In this study, we found that JEV vaccine immunization can provide cross-protection, but the adoptive transfer of CD8 T cells from JEV vaccine-immunized mice only partially protected naïve HHD Ifnar1–/– mice from ZIKV infection." (PMID 33101303, 2020). "ZIKV infection in IFNAR1−/− and wild-type (WT) mouse eyes resulted in increased intraocular pressure (IOP) and the development of chorioretinal atrophy." (PMID 31068433, 2019). "Estradiol-treated animals (estrous stage), which showed a thickened epithelial layer, were resistant to intravaginal ZIKV infection in anti-Ifnar1 mAb-treated Ifnlr1−/− and WT mice." (PMID 30655513, 2019). "We found that immune-modulated ZIKV infection with the anti-IFNAR1 antibody resulted in more robust induction of Tfh (CXCR5highPD-1high) and pre-Tfh (CXCR5mediumPD-1medium) than direct ZIKV infection without antibody treatment or uninfected control." (PMID 31455769, 2019). "We found that ZIKV infection caused RGC death, resulting in their significant loss in IFNAR1−/− mice." (PMID 31068433, 2019). "Taken together, these data suggest that R428 interferes with the canonical interaction of Axl and IFNAR1 in human SC to potentiate IFNAR-dependent antiviral state during ZIKV infection." (PMID 31311882, 2019). "To determine if CD4+T cells were protective against ZIKV infection we utilized the Ifnar1-/- mouse model of infection." (PMID 30212537, 2018). "We surmised that as the Ifnar1-/- mice were more sensitive to ZIKV infection than the immune competent C57BL/6J, and would therefore have higher antigen loads in the Ifnar1-/- mice resulting in stronger ZIKV-specific CD4+T cell responses." (PMID 30212537, 2018). "This was especially surprising as all of the Ifnar1-/- survive ZIKV infection with this dose and route." (PMID 30212537, 2018). "We selected testes for analysis because this tissue exhibits relatively high viral load in the A129 mouse model (IFNAR1 knockout) of ZIKV infection." (PMID 30511641, 2018).
ZIKV infection (continued). "To examine the lethality of ZIKV infection when the virus was administered by the i.a. route, we infected Ifnar1−/− mice with 104 or 105 PFU doses." (PMID 30333476, 2018). "The same group established an in utero transmission model of ZIKV infection using wild-type mice treated with this IFNAR-1 blocking monoclonal antibody." (PMID 28068342, 2017). "In terms of mortality all Stat2-/- and Ifnar1-/- mice succumbed to African ZIKV infections between day 6 to 8, with Stat2-/- mice displaying slightly higher early mortality as compared to Ifnar1-/- mice." (PMID 28278235, 2017). "Relevant ZIKV infection models have been developed in mice either using Ifnar1 knock-out (KO) mice in which the IFNAR receptor to IFN-I has been inactivated, or by blocking this receptor using a monoclonal antibody targeting the IFNAR1 receptor subunit (MAR1-5A3)." (PMID 37733807, 2023). "ZIKV infection via iVag inoculation was compared between WT, IFNε-/- and IFNAR1-/- mice." (PMID 36897927, 2023). "To determine the contribution of endogenous IFNε expression in the FRT, relative to other (conventional) type-I IFNs to prevent ZIKV infection, we compared the outcomes of intravaginal (iVag) infection of wildtype (WT), IFNε-/- or IFNAR1-/- mice with 5 X 105 FFU of ZIKV Puerto Rican stain PRVABC59." (PMID 36897927, 2023). "Combined, these data suggest that immune-competent mice are not susceptible to clinical or disseminated ZIKV infection through subcutaneous route of inoculation, unlike findings in IFNAR1-/- mice." (PMID 34410903, 2021). "Indeed, it has previously been shown that type I IFN signaling, not the levels of virus, mediated pathology following intravaginal ZIKV infection in Ifnar1+/− fetuses and placentas." (PMID 34379510, 2021). "Interestingly, SA14-14-2-vaccinated Ifnar1-/- mice were completely protected (6/6) against ZIKV infection, as compared with PBS-treated mice where 83.3% (5/6) mice succumbed to infection." (PMID 32556415, 2020). "ZIKV infection at embryonic day 6.5 (E6.5) or E7.5 in either wild-type (WT) immunocompetent mice treated with MAR1-5A3, a blocking anti-Ifnar monoclonal antibody, or in Ifnar1 deficient mice can recapitulate the CZS phenotype in vivo." (PMID 32544190, 2020). "In this study, we investigated the role of CD4+ T cells in the response to primary ZIKV infection via systemic (intravenous) and sexually transmitted (intravaginal) routes using LysMCre+Ifnar1fl/fl and Ifnar1-/- C57BL/6 mice for investigation of the CD8+ T cell response to ZIKV." (PMID 30677097, 2019). "We observed that DENV2-elicited CD8+ T cells mainly recognized epitopes in ZIKV NS3, NS5, prM and E, and that these cross-reactive CD8 T cell responses dominated during ZIKV infection in Ifnar1−/−and WT C57Bl/6 mice with Ifnar1 blockade (via pre-treatment with blocking anti-Ifnar1 Ab)." (PMID 31244855, 2019). "In addition, ZIKV infection of pregnant IFNAR1–/– mice led to severe fetal growth restriction and fetal demise, compared to control mice." (PMID 31652496, 2019). "In this study, we tested the efficacy of convalescent plasma IgG hyperimmune product (ZIKV-IG) isolated from individuals with high neutralizing anti-ZIKV titers as a therapeutic candidate against ZIKV infection using a model of ZIKV infection in Ifnar1−/− mice." (PMID 31285451, 2019). "For vertical transmission studies, two models were developed: WT C57BL/6 females were crossed to WT C57BL/6 sires, and then dams were given the anti-Ifnar1 antibody immediately before ZIKV infection; or Ifnar1−/− dams were crossed to WT sires and then inoculated with ZIKV." (PMID 30384472, 2018). "Hematology on CD4+T cell depleted or control Ifnar1-/- mice following ZIKV infection." (PMID 30212537, 2018).
ZIKV infection (continued). "In previous studies, ZIKV infection can cause severe damage to testicular morphology and massive inflammatory cell infiltration in C57BL/6 mice treated with anti-Ifnar1 blocking monoclonal antibody or Ifnar1-/- mice, and ZIKV infection was thought a major contributor of the testicular damage." (PMID 37732785, 2023). "Therefore, we hypothesized that the consequences of CD4+ T cell depletion during ZIKV infection would be difficult to detect in 4-week-old Ifnar1-/- mice." (PMID 30212537, 2018). "Consequently, because ZIKV and DENV do not efficiently antagonize type I interferon (IFN) signaling in mice as they would do in humans, animals were treated with a single dose of blocking monoclonal antibody against mouse IFNAR1 to facilitate ZIKV infection and dissemination." (PMID 29985932, 2018). "Furthermore, wt mice treated with MAR1-5A3 (a monoclonal antibody (mAb) that blocks the IFN-α/β receptor (IFNAR)) were susceptible to ZIKV infection but did not demonstrate a same neurological phenotype as Ifnar1−/− mice." (PMID 28608813, 2017). "We assessed rimantadine antiviral effects in vivo using a preclinical ZIKV infection model comprising C57BL/6 mice and transient blockade of the interferon alpha receptor type 1 (IFNAR1)." (PMID 39177307, 2024). "Here, we optimized the established anti-IFNAR1 treated, Rag1−/− (AIR) mouse model of ZIKV infection to examine the consequence of vertical transmission on neonate survival and postnatal brain development." (PMID 35379362, 2022). "Following previous clinical studies, in our cohort, the determination of the trimester of pregnancy in which ZIKV infection occurs was a strong predicting factor for CZS outcome, along with IFNAR1 genotype." (PMID 34899713, 2021). "Pregnant IFNAR1 knockout mice and pregnant C57BL/6 mice treated with anti-IFNAR1 monoclonal antibody represent a good model to investigate ZIKV infection during pregnancy." (PMID 32373111, 2020). "Intradermal electroporation of as few as 1 μg of this mRNA-based ZIKV vaccine induced potent humoral and cellular immune responses in BALB/c and especially IFNAR1-/- C57BL/6 mice, resulting in a complete protection of the latter mice against ZIKV infection." (PMID 31450775, 2019). "Taken together, these data suggest that in WT mice with transient Ifnar1 blockade, prior DENV immunity controls ZIKV infection in both maternal and fetal tissues via DENV-exposed memory CD8+ T cells." (PMID 30072692, 2018). "To evaluate the role of the DENV-immune Ab response in mediating protection or enhancement during ZIKV infection, we collected sera from naive and DENV2-infected Ifnar1−/− mice on day 28 after infection." (PMID 29129917, 2017). "Thus, we used adult type I IFN receptor IFNAR knockout (Ifnar1−/−) mice as a ZIKV infection mouse model to examine proinflammatory responses in the CNS and the neuropathogenesis of ZIKV infection." (PMID 37191498, 2023). "Both mRNA and protein levels of PARP11 were induced in WT but not IFNAR1−/− cells in response to IFNα or IFNβ stimulation and ZIKV infection." (PMID 34187568, 2021). "Previous studies by us and others have independent shown that antibodies against JEV are cross-reactive to ZIKV, but passive transfer of JEV antisera fails to protect ZIKV infection in Ifnar1–/– mice." (PMID 33101303, 2020). "Our data also showed that ZIKV infection by a systemic route (i.p.)resulted in elevated IOP in IFNAR1−/− but not the WT mice." (PMID 31068433, 2019). "In support of this hypothesis, we saw that Ifnar1−/− mice had a very similar delayed pattern of sensor and Irf7 induction in the FRT after ZIKV infection." (PMID 31554802, 2019). "Moreover, to study the effect of ZIKV infection during pregnancy, a trans-placental transmission mouse model of ZIKV has been developed by knocking out IFNAR1." (PMID 31635238, 2019).
ZIKV infection (continued). "In the presence of anti-IFNAR1 antibody pre-treatment, inactivated ZIKV induced fewer Tfh cells, or cells of other helper T cell subsets, and much less antibody response, compared with live ZIKV infection." (PMID 31455769, 2019). "Importantly, treatment with either JAKi or small interfering RNA (siRNA) targeting the interferon alpha receptor 1 (IFNAR1) did not rescue ZIKV infection in the AXL KO cells in contrast to the results from the astrocytes." (PMID 40062839, 2025). "Studies have indicated that mice lacking the IFNAR gene were more vulnerable to Zika virus infection, whereas chicken fibroblast cell lines lacking the IFNAR1 gene could greatly enhance the replication efficiency of duck Tembusu virus." (PMID 39100665, 2024). "Thus, antibody response is unlikely to mediate the protection of JEV vaccine-immunized HLA-transgenic or non-transgenic Ifnar1–/– mice from ZIKV infection." (PMID 33101303, 2020). "On the other hand, mice deficient in IFNAR1 are susceptible to ZIKV infection and it has been demonstrated that systemic ZIKV spreading relies on IFNAR1 expression in the hematopoietic compartment, whereas spreading within the CNS requires IFNAR1 expression on non-hematopoietic cells." (PMID 32106582, 2020). "While significant IFNAR1 downregulation was observed in WT and PARP11−/− A549 cells in response to VSV infection, the IFNAR1 protein level showed no obviously change in both WT and PARP11−/− A549 cells upon ZIKV infection." (PMID 34187568, 2021). "The result showed that ZIKV infection did not obviously change IFNAR1 protein level, while VSV infection decreased IFNAR1 protein level significantly." (PMID 34187568, 2021). "Similar to exogenous IFN treatment, ZIKV infection also induced PARP11 mRNA and protein expressions in WT but not in IFNAR1−/− A549 cells." (PMID 34187568, 2021). "Previous work has demonstrated that wild-type immunocompetent mice are resistant to ZIKV pathogenesis but that mice lacking alpha/beta interferon (IFN-α/β) signaling (e.g., Ifnar1−/−, A129, AG129, Irf3−/− × Irf5−/− × Irf7−/−) succumb to ZIKV infection." (PMID 28270583, 2017). "This appears to be the case with mouse models of ZIKV infection, as younger mice tend to suffer much more severe disease burden during ZIKV infection than older mice both in the literature as well as in our hands we saw 100% lethality independent of dose in 4-week-old Ifnar1-/- mice." (PMID 30212537, 2018).
COVID-19 (58 papers, 2021 to 2026). A disease caused by infection with severe acute respiratory syndrome coronavirus 2. "Patients with severe COVID-19 with IFNAR1 deficiency treated with IFN-γ showed increased oxygen saturation (SpO2) to 94% in the nine days of hospitalization." (PMID 38003785, 2023). "To do this, we pose the following research question: do the risk variants in SNVs of IFNAR1 or IFNAR2 of patients with severe COVID-19 affect the antiviral immune response or lead to poor outcomes compared to noncarriers individuals of risk variants?" (PMID 38003785, 2023). "IFNAR2 and IFNAR1 genes have been associated with severe COVID-19 in populations from the United Kingdom, Africa, and Latin America." (PMID 38003785, 2023). "Compared to IFNAR2, studies of genetic variants of IFNAR1 and COVID-19 had a small sample size; however, the results in IFNAR1 and infection by SARS-CoV-2 are relevant." (PMID 38003785, 2023). "The overexpression of interferon suggests an effective protection against ARDS, whereas recent studies demonstrated that patients with IFNAR1 deficiency were prone to develop severe forms of COVID-19." (PMID 36009234, 2022). "Consistently, patients with IFNAR1 deficiency are prone to severe COVID-19, indicating that IFNAR1 plays a central role in host innate immunity." (PMID 35336954, 2022). "A new patient with autosomal recessive IFNAR1 deficiency and critical COVID-19 has been recently reported, and a patient with TBK1 deficiency also has been identified." (PMID 35091979, 2022). "There are few genetic association studies of IFNAR1 in COVID-19 in the literature." (PMID 38003785, 2023). "Patients with IFNAR1 deficiency develop a severe form of COVID-19." (PMID 38003785, 2023). "Furthermore, inherited autosomal deficiencies (both recessive and dominant) in IFNAR1/2 have been identified in highly severe COVID-19 patients." (PMID 36672763, 2022). "Inherited IFNAR1 deficiency underlies critical COVID-19 probably due to its broad cellular impact." (PMID 34413140, 2021). "Further bioinformatic analyses have highlighted the potential role of rare variants in interferon receptor genes IFNAR1 p.Val168Leu, is associated with a reduced risk of severe COVID-19, while rare pathogenic variants in both IFNAR1 and IFNAR2 may impair antiviral signaling." (PMID 40410684, 2025). "However, as others have shown that IFNs play an ambiguous role during COVID-19, further experiments (e.g., using IFNAR1-deficient animals or type I IFN blocking antibodies) will be required to address the direct impact of type I IFNs on maVie16 clearance in vivo." (PMID 35023830, 2022). "Strikingly, although only a few individuals have been identified with rare AR IFNAR1 or IFNAR2 variants, COVID-19 lethality rates are 57% in these individuals." (PMID 38932404, 2024). "Epitope mapping analyses revealed that the auto-abs to type I IFN in COVID-19 patients recognized the receptor binding region of IFN-α2 to IFNAR1." (PMID 38647550, 2024). "This systematic review aimed to describe IFNAR1 and IFNAR2 variants associated with COVID-19 susceptibility and severity." (PMID 38003785, 2023). "In 23 people from the 659 patients with severe COVID-19 autosomal recessive (IRF7, IFNAR1) and autosomal dominant (TLR3, UNC93B1, TICAM1, TBK1, IRF7, IRF3, IFNAR1, IFNAR2) deficiencies were found." (PMID 36142877, 2022). "In particular, autosomal-recessive deficiencies in IRF7 and IFNAR1 and autosomal-dominant deficiencies in TLR3, TBK1, IRF3, IRF7, IFNAR1 and IFNAR2 genes have been found in a small percentage of patients with severe influenza and COVID-19." (PMID 35846766, 2022). "The relevance of studying genetic variants in IFNAR1 and IFNAR2 in patients with COVID-19 is that there are previous reports of polymorphisms in these genes associated with response to interferon therapy, like rs9984273 (IFNAR2) located in a binding motif for the glucocorticoid receptor." (PMID 38003785, 2023).
COVID-19 (continued). "It has been found that about 3.5% of COVID-19 patients had known autosomal-recessive (AR) deficiencies [interferon regulatory factor 7 (IRF7) and IFNAR1] and autosomal-dominant deficiencies (AD) [toll-like receptor 3 (TLR3), UNC93B1, TICAM1, TBK1, IRF3, IRF7, IFNAR1, and IFNAR2]." (PMID 34335535, 2021). "A bioinformatics analysis of the single-cell and bulk RNA-seq profiling of COVID-19 patients’ data revealed a significant upregulation of cGAS-STING signalling pathway genes (TMEM173, IRF3, NFKB1, CGAS, IFNAR1, and TBK1) in the lung." (PMID 39459875, 2024). "This study identified 30 nodes associated with cytokine storm, ARDS, and inflammatory process of COVID-19, namely, IL-6, IL-6R, NF-κB, IL-2, IL-2RA, IFNA2, IFNAR1, COX5A, and COX411." (PMID 39640429, 2024). "Receptors for type I (IFNAR1 and 2) and III (IL10RB) interferons drive inflammation mediated by NK and CD8+ T cells, and IL-10RB binds IL-10 whose levels are a severity predictor in COVID-19." (PMID 35659055, 2022). "Finally, we found IFNAR1 and IFNAR2, a receptor for type I interferon (IFNα) to be upregulated in the CD4+ TCM and classical monocytes of the COVID-19 patients, compared to the others." (PMID 36532041, 2022). "Antibodies induced by rMeV-preS were uniformly high in all four animal models including cotton rats, IFNAR−/− mice, IFNAR1−/−-hCD46 mice, and Syrian golden hamsters and were significantly higher than antibody titers of human sera from convalescent COVID-19 patients." (PMID 33688034, 2021).